CSNK1E (casein kinase 1 epsilon)
Description:
Casein kinases are operationally defined by their preferential utilization of acidic proteins such as caseins as substrates (Probable). Participates in Wnt signaling. Phosphorylates DVL1. Phosphorylates DVL2. Phosphorylates NEDD9/HEF1 (By similarity). Central component of the circadian clock. In balance with PP1, determines the circadian period length, through the regulation of the speed and rhythmicity of PER1 and PER2 phosphorylation. Controls PER1 and PER2 nuclear transport and degradation (By similarity). Inhibits cytokine-induced granuloytic differentiation.
Synonyms: CKIe; HCKIE; CKIepsilon
Tractability: Small molecule: an approved drug acts on it; a structure with a bound ligand is known; a high-quality ligand is known; it belongs to a druggable protein family. PROTAC: it is named in the literature on targeted protein degradation; ubiquitination databases record sites on it; its protein half-life has been measured; a small molecule that binds it is known.
Target class: CK1 protein kinase group; Enzyme; CK1 protein kinase CK1 family; Protein Kinase; Kinase
Chemical probes: JNJ-78386204 (high quality), MU1742 (high quality), PF-4800567 (high quality)
Safety:
Unwanted effects reported when the protein is acted on. In parentheses: how it was acted on, where the effect was seen, and who reports it.
heroin dependence (source: ClinPGx)
Gene: Protein-coding gene on chromosome 22 (38,290,691 to 38,320,044, reverse strand). Ensembl gene ENSG00000213923.
Subcellular location: Cytoplasm; Nucleus
Subcellular location (Human Protein Atlas): Cytosol; Nucleoplasm
Pathways (Reactome):
Cell Cycle: AURKA Activation by TPX2; Loss of Nlp from mitotic centrosomes; Loss of proteins required for interphase microtubule organization from the centrosome; Recruitment of NuMA to mitotic centrosomes; Recruitment of mitotic centrosome proteins and complexes; Regulation of PLK1 Activity at G2/M Transition; Ubiquitin-Mediated Degradation of Phosphorylated Cdc25A
Circadian clock: Phosphorylation and nuclear translocation of the CRY:PER:kinase complex; The CRY:PER:kinase complex represses transactivation by the BMAL:CLOCK (ARNTL:CLOCK) complex
Metabolism of RNA: Major pathway of rRNA processing in the nucleolus and cytosol
Organelle biogenesis and maintenance: Anchoring of the basal body to the plasma membrane
Signal Transduction: WNT mediated activation of DVL
Gene Ontology:
Molecular function: protein binding; protein kinase activity; protein serine/threonine kinase activity; RNA binding; ATP binding; protein serine kinase activity
Biological process: canonical Wnt signaling pathway; negative regulation of small GTPase mediated signal transduction; non-canonical Wnt signaling pathway; protein phosphorylation; regulation of protein localization; circadian regulation of gene expression; DNA repair; endocytosis; positive regulation of canonical Wnt signaling pathway; positive regulation of non-canonical Wnt signaling pathway; positive regulation of proteasomal ubiquitin-dependent protein catabolic process; regulation of circadian rhythm; signal transduction; cellular response to nerve growth factor stimulus; circadian behavior; positive regulation of amyloid-beta formation; positive regulation of Wnt signaling pathway; regulation of Wnt signaling pathway
Cellular component: cytoplasm; cytosol; nucleoplasm; nucleus; growth cone; neuronal cell body; ribonucleoprotein complex
Genetic constraint (gnomAD): Loss-of-function variants: 17 observed, 43.37 expected, observed/expected ratio (o/e) 0.39, 90% interval 0.27 to 0.59. The upper end of that interval is the gene's LOEUF score, 0.59, which puts it in group 2 of 6, group 1 being the genes least tolerant of losing a copy. Missense variants: 386 observed, 589.45 expected, observed/expected ratio (o/e) 0.65, 90% interval 0.6 to 0.71. Synonymous variants: 241 observed, 238.58 expected, observed/expected ratio (o/e) 1.01, 90% interval 0.91 to 1.12.
Homologues: Orthologues: guinea pig CSNK1E (99% identical), mouse Csnk1e (99% identical), chimpanzee CSNK1E (98% identical), rat Csnk1e (98% identical), tropical clawed frog csnk1e (97% identical), macaque CSNK1E (77% identical), pig CSNK1E (77% identical), rabbit CSNK1E (77% identical), Drosophila melanogaster dco (67% identical), Caenorhabditis elegans kin-20 (58% identical). Paralogues in human: CSNK1D (84% identical), CSNK1A1 (55% identical), CSNK1A1L (52% identical), CSNK1G3 (48% identical), CSNK1G1 (45% identical), CSNK1G2 (45% identical), TTBK1 (34% identical), TTBK2 (32% identical), VRK1 (25% identical), VRK2 (24% identical), CDC7 (20% identical), VRK3 (18% identical).
Diseases named in the same sentence as CSNK1E in open-access papers:
CSNK1E is named in the same sentence as 62 diseases in open-access papers, as found by Europe PMC text mining. Sharing a sentence is not in itself a finding about the gene and the disease. The quoted sentences say what the papers report.
breast carcinoma (12 papers, 2010 to 2022). "On the other hand, high casein kinase 1 epsilon (CSNK1E) is correlated with better prognosis in breast cancer and the loss of CSNK1E is associated with poorer prognosis in patients with low stage oral cancer and in patients with hepatocellular carcinoma." (PMID 30112110, 2018). "Here we identify CSNK1E, the gene encoding casein kinase 1 epsilon (CK1ε) as required specifically for the proliferation of breast cancer cells with activated β-catenin and confirm its role as a positive regulator of β-catenin-driven transcription." (PMID 20126544, 2010). "Sequencing of mammary carcinoma samples by Fuja and colleagues revealed that the casein kinase 1 epsilon (CK1ε) gene was mutated in this disease; CK1ε was found to be mutated within its N-terminal region with approximately 15% incidence." (PMID 20507565, 2010). "By using an RNAi-mediated loss-of-function screening approach, we have identified CSNK1E, a member of the casein kinase family, as an essential regulator of β-catenin activity and proliferation in breast cancer cell lines." (PMID 20126544, 2010). "High levels of CSNK1E expression have been associated with a poor prognosis (i.e., shorter overall survival) in patients with ovarian cancer, but have been associated with a favorable prognosis in subsets of patients with breast cancer." (PMID 35368886, 2022). "Furthermore, mutations in CSNK1E decrease cell adhesion and promote cell migration in breast cancer." (PMID 30112110, 2018). "One of the genes that were found mutated in breast cancer is casein kinase 1 epsilon (CK1ε)." (PMID 20507565, 2010). "CSNK1E encodes a beta-catenin destruction complex and is involved in aberrations of the Wnt/beta-catenin signaling pathway, which lead to beta-catenin oncoprotein accumulation in the nucleus; elevated expression in breast cancer patients with relapses was observed in the current study." (PMID 24098497, 2013). "In the subjects with three night shifts, SNPs in BMAL1 (rs2278749), BMAL2 (rs2306074), CSNK1E (rs5757037), NPAS2 (rs17024926), PER3 (rs1012477) and MTNR1A (rs131113549) were associated with decreased breast cancer risk." (PMID 23822714, 2013). "Utilizing complementary unbiased functional genomics approaches, we have identified CSNK1E as a gene essential for Wnt/β-catenin signaling and survival in a subset of breast cancers that exhibit aberrant β-catenin activity." (PMID 20126544, 2010). "Existing reports have shown that oral squamous cell carcinoma, breast cancer, and colorectal cancer patients with a lower expression of CSNK1E exhibited a considerably longer overall survival rate than patients with higher expression of CSNK1E." (PMID 35877357, 2022). "In addition, women in this exposure group carrying at least one variant allele of several SNPs in the other core circadian genes such as BMAL2, CSNK1E, NPAS2 and PER3 had a noteworthy reduced risk of breast cancer." (PMID 23822714, 2013). "Having determined that CSNK1E regulates Wnt/β-catenin signaling, as well as proliferation of β-catenin-positive breast cancer cells, we next determined whether CSNK1E is potentially involved in promoting β-catenin-dependent oncogenic transformation in breast cancer." (PMID 20126544, 2010). "Interestingly, suppression of CSNK1D, which is highly homologous to and has overlapping function with CSNK1E, did not affect proliferation of β-catenin positive cancer cell lines, suggesting a specific role for CSNK1E, at least in the context of these breast cancer cells." (PMID 20126544, 2010). "These were Estrogen Biosynthesis (HSD17B7 and HSD17B12), Estrogen-Dependent Breast Cancer Signaling (HSD17B7 and HSD17B12), Hepatic Fibrosis/Hepatic Stellate Activation (CD14 and CD40), Tight Junction Signaling (CDSF1 and OCLN), and Dopamine-DARPP32 Feedback in cAMP Signaling (CACNAID and CSNK1E)." (PMID 23759029, 2013).
breast carcinoma (continued). "Many of the associations, such as PER3 (rs1012477), CSNK1E (rs1534891) and CLOCK (rs11133373, rs3749474), are novel in relation to breast risk but may not be specific to breast cancer, because they have also been found to be associated with prostate and colorectal cancer risk." (PMID 23822714, 2013).
ovarian carcinoma (7 papers, 2015 to 2024). A malignant neoplasm originating from the surface ovarian epithelium. "Inhibition of CSNK1E has been show to selectively inhibit tumor cell development, and elevated CSNK1E expression is associated with poor prognosis in patients with ovarian cancer and malignant melanoma." (PMID 39267750, 2024). "A GWAS and a replication study for epithelial ovarian cancer (EOC) analyzed variants of several circadian genes (ARNTL, CRY2, CSNK1E, NPAS2, PER3, REV1, and TIMELESS) and two transcription factors (KLF10 and SENP3)." (PMID 30873119, 2019). "The goal of the current study was to examine single nucleotide polymorphisms (SNPs) in circadian genes BMAL1, CRY2, CSNK1E, NPAS2, PER3, REV1 and TIMELESS and downstream transcription factors KLF10 and SENP3 as predictors of risk of epithelial ovarian cancer (EOC) and histopathologic subtypes." (PMID 26807442, 2015). "We further evaluated the correlations between PER1 and these 10 interacting proteins based on the GEPIA database and found that the expression of PER1 in ovarian cancer was correlated with that of ARNTL, CLOCK, CRY1, CRY2, CSNK1D, CSNK1E, NPAS2, and PER3." (PMID 34220965, 2021).
glioma (5 papers, 2016 to 2025). A benign or malignant brain and spinal cord tumor that arises from glial cells (astrocytes, oligodendrocytes, ependymal cells). "Among the 13 pathway-related genes, only CSNK1E showed identical expression pattern with circadian pathway index, indicating a positive correlation to the circadian pathway alteration in glioma." (PMID 34224318, 2021). "Two genes that play important roles in circadian clock regulation, casein kinase-1 epsilon (CK-1ε) and the nuclear receptor NR1D2, were found to regulate GBM cell survival and were proposed as targets for glioma treatment." (PMID 34371781, 2021).
melanoma (5 papers, 2021 to 2024). A malignant, usually aggressive tumor composed of atypical, neoplastic melanocytes. "What’s more, We conducted three phenotypic experiments following the knockdown of CSNK1E in human melanoma cell lines to enhance the credibility of our bioinformatics conclusions." (PMID 39872053, 2024). "The analysis focused only on CSNK1A1, CSNK1D, and CSNK1E, not on CSNK1G; CSNK1A1 alterations are dominant in clear cell renal cell carcinoma, and pancreas cancer, CSNK1D in liver and sarcoma, and CSNK1E in melanoma and liver." (PMID 33861751, 2021). "Interestingly, we found that a higher expression of CSNK1E is correlated with shorter survival in melanoma patients." (PMID 34769455, 2021). "In the current study, we found that higher expressions of FGD1, CSNK1E, and IRX3 are correlated with shorter survival of melanoma patients." (PMID 34769455, 2021). "By analyzing the TCGA genomics, we also found that the gene alteration rates in the melanoma TCGA dataset were 12% for DDX60, 5% for CSNK1E, 2.8% for FGD1, 2.1% for GBP4, 4% for IFIH1, 1% for DOK1, and 0.7% for IRX3, and these alterations were not significantly correlated with mRNA expression." (PMID 34769455, 2021).
bipolar disorder (4 papers, 2010 to 2024). A disorder of the brain that causes unusual shifts in mood, energy, activity levels and the ability to carry out day-to-day tasks. "It was also observed to interact with rs6442925 in the BHLHB2 gene and rs1534891 in the CSNK1E gene in association with bipolar disorder." (PMID 30696097, 2019). "In particular, the CSNK1E gene has been linked to the pathophysiology of schizophrenia and bipolar disorder which are the main conditions for which antipsychotics are used." (PMID 29850476, 2018). "The findings highlighted significant associations between mood disorders and specific alleles, notably TIMELESS rs4630333 and CSNK1E rs135745, in relation to major depressive disorder and bipolar disorder, as well as a notable association with a CLOCK gene haplotype." (PMID 39584972, 2024). "Perhaps the most convincing evidence so far has emerged from bipolar disorder with some evidence of association with period homolog 3 (Drosophila) (PER3), ARNTL, basic helix-loop-helix family, member e40 (BHLHE40), casein kinase 1, epsilon (CSNK1E), and CLOCK." (PMID 20174623, 2010).
sarcoma (3 papers, 2016 to 2024). A usually aggressive malignant neoplasm of the soft tissue or bone. "Knocking down CSNK1E in a human sarcoma cell line led to growth inhibition of cells, and CSNK1E was found to be upregulated in ten different human cancer tissues compared to normal tissue." (PMID 27492458, 2016).
cognitive deficits (2 papers, 2023 to 2024). "It has been studied for decades how CSNK1E functions physiologically and it was found to be associated with cognitive deficits in schizophrenia, survival of several cancer, heroin addiction, and opioid sensitivity." (PMID 38302916, 2024). "In addition, PRKCD, RASGRP1, SYNCRIP, CSNK1E, and CBX3 were involved in the regulation of synaptic plasticity and were associated with cognitive impairment caused by neurological diseases." (PMID 37106826, 2023).
glioblastoma (2 papers, 2018 to 2022). The most malignant astrocytic tumor (WHO grade IV). "In glioblastoma samples, CSNK1E was expressed at significantly higher levels than in normal tissues." (PMID 35877357, 2022). "In our previous work, we identified casein kinase 1 ε (CK1ε, also known as CSNK1E) as a potential survival factor in glioblastoma." (PMID 30206363, 2018).
hepatocellular carcinoma (2 papers, 2018 to 2023). A malignant tumor that arises from hepatocytes. "In total, 563 circadian genes were differently expressed in hepatocellular carcinoma; three of them—CSNK1D, CSNK1E and NPAS2—had a high correlation with the overall survival rate in LIHC patients." (PMID 37240761, 2023).
marginal zone lymphoma (2 papers, 2022 to 2023). A usually indolent mature B-cell lymphoma, arising from the marginal zone of lymphoid tissues. "Umbralisib is a dual inhibitor of phosphatidylinositol 3-kinase delta (PI3Kδ) and casein kinase 1 epsilon (CK1ε) for treating marginal zone lymphoma (MZL) and follicular lymphoma (FL)." (PMID 35126158, 2022).
mental disorder (2 papers, 2020 to 2024). A disease that has its basis in the disruption of mental process. "Two of these were found in the mRNA sequence of Csnk1e, which is annotated in the Rat Genome Database (RGD) as a gene associated with neurodegenerative diseases and mental disorders." (PMID 32429546, 2020). "Of note, BD risk was also not enriched in the MAGMA analyses, suggesting that BHLHE41 (which was also identified with INRICH at the gene level and CSNK1E are primarily associated with treatment response and neither with pathogenesis of BD nor any other psychiatric disease risk studied." (PMID 39372797, 2024).
prostate carcinoma (2 papers, 2018 to 2025). A carcinoma that arises from epithelial cells of the prostate gland. "Eight of these, located in four genes, NPAS2 (2 SNPs), CSNK1E (3 SNPs), CRY1 (2 SNPs), and CRY2 (1 SNP), were significantly associated with prostate cancer risk." (PMID 30518396, 2018).
Alzheimer disease (1 paper, 2023). A progressive, neurodegenerative disease characterized by loss of function and death of nerve cells in several areas of the brain leading to loss of cognitive function such as memory and language. "In our study, employing the TPP method, we successfully identified NSCTN and CSNK1E as direct protein targets of deoxycholic acid (DCA), an MBA associated with Alzheimer's disease." (PMID 39883374, 2023).
Ataxia (1 paper, 2025). Ataxia refers to impaired coordination of voluntary muscle movement. "We describe a long CGG expansion (CGGn = 745) in the 5′‐UTR of CSNK1E at the fragile FRA22A site as a possible cause of progressive myoclonic epilepsy with ataxia and progressive cognitive deterioration." (PMID 40751262, 2025).
autism (1 paper, 2024). Persistent deficits in social interaction and communication and interaction as well as a markedly restricted repertoire of activity and interest as well as repetitive patterns of behavior. "NFIX has been predicted to target 28 autism risk genes, including DIP2C and CSNK1E." (PMID 39363111, 2024).
bladder cancer (1 paper, 2022). "Bioinformatic database screening for bladder cancer followed by gene co-expression network analysis revealed six new genes (PPARD, CST4, CSNK1E, PTPN14, ETV6, and ADRM1) and several new miRNAs, including miR-124, as drivers in the development and progression of bladder cancer." (PMID 36362406, 2022).
brain cancer (1 paper, 2014). A primary or metastatic malignant neoplasm affecting the brain. "The kinase CSNK1E had been previously associated only with non-brain cancers, while HIPK2, LYN, and EPHB4 have been suggested as targets for anti-tumor therapies." (PMID 25236784, 2014).
epileptic encephalopathies (1 paper, 2025). "Recently, a CGG repeat expansion and increased CSNK1E DNA methylation have been shown to be associated with developmental and epileptic encephalopathies." (PMID 40751262, 2025).
leukemia (1 paper, 2021). A malignant (clonal) hematologic disorder, involving hematopoietic stem cells and characterized by the presence of primitive or atypical myeloid or lymphoid cells in the bone marrow and the blood. "Positive associations of CSNK1E in CLLE and CBX2 in LAML reached significance (ρ = 0.8750 and 0.8018, pFDR = 0.0306), consistent with their positive associations with many gene targets in these leukemia types." (PMID 33676569, 2021).
lipid metabolism disorders (1 paper, 2024). "BHLHE40 was found to promote obesity through various pathways, while PPP1CB and CSNK1E counteracted lipid metabolism disorders, and modulated cytokines, immune receptors, T cells, and monocytes." (PMID 39351493, 2024).
liver cancer (1 paper, 2021). An epithelial or non-epithelial malignant neoplasm that arises from the liver. "To explore the expression levels of genes (CSNK1D, CSNK1E, and NPAS2) in liver cancer, we compared the mRNA expression levels of tumor and normal tissues." (PMID 34149816, 2021). "We found that higher expression levels of CSNK1D, CSNK1E, and NPAS2 were significantly related to shorter OS of liver cancer patients." (PMID 34149816, 2021). "Additionally, in the liver cancer cell experiment, similar results were obtained, in which the CSNK1D, CSNK1E, and NPAS2 mRNA expression levels were strongly upregulated compared with those in normal liver cells." (PMID 34149816, 2021).
lymphoma (1 paper, 2022). A malignant (clonal) proliferation of B- lymphocytes or T- lymphocytes which involves the lymph nodes, bone marrow and/or extranodal sites. "Phosphatidylinositol 3-kinase delta (PI3Kδ) inhibitors are proved to be promising drugs for treating lymphoma, and casein kinase 1 epsilon (CK1ε) is also a potent target for the therapy of lymphoma." (PMID 35126158, 2022).